LINC01252 (long independently transcribed non-coding RNA 1252)
Gene: Long non-coding RNA gene on chromosome 12 (11,499,742 to 11,590,369, forward strand). Ensembl gene ENSG00000247157.
Diseases named in the same sentence as LINC01252 in open-access papers:
LINC01252 is named in the same sentence as 1 disease in open-access papers, as found by Europe PMC text mining. Sharing a sentence is not in itself a finding about the gene and the disease. The quoted sentences say what the papers report.
tumor (1 paper, 2022). "Interestingly, qRT-PCR results indicated that the expression of AP001619.1, AC020917.2, LINC01252, AC010789.2, AL356804.1, ZFHX2-AS1, AC002066.1, and AC008752.2, AC012313.5 was significantly higher in normal tissue while expression of LINC02542 was similar between normal and tumor tissue." (PMID 35965536, 2022).